GLI2 (GLI family zinc finger 2)
Diseases named in the same sentence as GLI2 in open-access papers (continued):
Sharing a sentence is not in itself a finding about the gene and the disease.
tumor (continued). "These latter events in GLI2 and MYCN further support a driver role for these genes in Shh-MB, and are clinically important as their presence in a tumor will likely render them unresponsive to Sonic Hedgehog pathway inhibition using small molecules." (PMID 33741928, 2021). "Primary tumor growth and metastatic outgrowth can be suppressed by ablation of SPP1, a downstream target of GLI2, emphasizing its role in promoting tumor aggressiveness." (PMID 34888306, 2021). "Firstly, we restored the expression of GLI2 in HGC-27 transfected with miR-144-3p mimics, and the results showed that the tumor suppressive effects of miR-144-3p were reversed." (PMID 34657624, 2021). "In BC xenograft tumors, it significantly reduces tumor growth, which is accompanied by decreased PTCH, SMO, Gli1, and Gli2 expression." (PMID 34381705, 2021). "In most tumor types, GLI1 and GLI2 follow a similar pattern of expression and are equally correlated with HH and TGFB genes." (PMID 32879407, 2020). "Circ-STAT3 facilitates cell proliferation, invasion, migration, stemness and tumor growth in HB via up-regulation of STAT3 and Gli2, indicating circ-STAT3 as a putative biomarker for HB." (PMID 32493490, 2020). "Consistent with our previous study using 2D films, expression of ITGB3, GLI2, and PTHRP by tumor cells cultured on 3D scaffolds increased with increasing substrate modulus due to interactions between integrins and growth factors." (PMID 32967150, 2020). "For example, in two Hh pathway-dependent mouse basal cell carcinoma models, cilia deletion was able to inhibit tumor growth induced by an activated form of SMO, but also promote tumor growth induced by activated GLI2." (PMID 33339422, 2020). "In contrast, GANT58 reduced expression of ITGB3, GLI2, and PTHRP in tumor cells cultured on both 2D films and bone-like 3D scaffolds, which highlights the potential of Gli2 inhibitors for blocking TIBD." (PMID 32967150, 2020). "This paracrine mechanism is characterized by binding of tumor-secreted Hh ligands (SHH, Indian Hedgehog (IHH), or Desert Hedgehog (DHH)) to PTCH1 receptors, and elevated levels of GLI1, GLI2, PTCH1, and SMO genes in the tumor-adjacent stroma." (PMID 31658643, 2019). "In contrast, patients with low expression of GLI2 and SOX2 in the tumor had <60% of chance of cancer relapse." (PMID 30382189, 2019). "To explore the role of the GLI family proteins (include Gli1, Gli2, Gli3) in the onset and development of HCC, we examine tumor and matched adjacent normal tissue samples from 10 patients with HCC." (PMID 31616295, 2019). "The tumor had a highly rearranged genome with high-level focal amplifications of MYCN (319 CN; 660 FPKM), CCND2 (123 CN; FPKM 2516) and GLI2 (11 CN; FPKM 24)." (PMID 30262806, 2018). "Immunohistochemical analyses of GLI1, GLI2 and PTCH1 demonstrated that GANT61 was able to specifically inhibit Hh signaling in the tumor." (PMID 28208838, 2017). "These assays revealed an increased percentage of GLI2 positive nuclei both in the epidermis and BCC tumour masses of K14-CreER/Rosa-SmoM2 mouse skin (P < 0.01, N = 3), confirming increased Hedgehog signalling activity." (PMID 28820907, 2017). "Here, we report the identification of kinesin family member 20A (KIF20A) as a novel downstream target of Gli2, which is important for HCC proliferation and tumor growth." (PMID 27036048, 2016). "The human tumor data paralleled our cell line findings in that there was high PTCH1, SMO, GLI2, and GLI3 mRNA, but low GLI1 mRNA." (PMID 27793025, 2016). "We were able to demonstrate that GANT61 alone or in combination with IR significantly reduced gene expression of the main Hh target genes GLI1, GLI2 and PTCH1 in the tumor cells, but also in the surrounding stroma." (PMID 27713179, 2016).
tumor (continued). "In keratinocytes and MB cells, SOCS1 was found to be a direct target of GLI2, blocking the IFN-γ/STAT1 pathway and inhibiting cell cycle arrest and downregulating anti-tumor immunity." (PMID 26988232, 2016). "Specifically, in panels D, a Gli1 molecule and a GLI2 molecule had weak expressions; the expressions of E-cadherin and SMAD-7 were significantly increased in the tumor areas, and the differences were statistically significant." (PMID 25895132, 2015). "GLI2 expression and osteolytic ability of metastatic tumor can be inhibited by abolishing TGFβ signaling, indicating SMO-downstream regulation of GLI2 via TGFβ cascade." (PMID 26343727, 2015). "Together, GLI2 promotes CIN and the accumulation of chromosomal abnormalities, which drive tumor formation." (PMID 24481442, 2014). "Western blot analyses of tumor tissues revealed that treatment with GANT61 indeed down-regulated Gli1 and Gli2 in tissues." (PMID 24533083, 2014). "Together, our study elucidates the tumor protective function of SPOP through inhibiting Hh/Gli2 pathway, and the possible molecular mechanism of Gli2 stability regulated by SPOP." (PMID 25204354, 2014). "While most studies on HHI resistance have focused on tumor‐intrinsic mechanisms, including canonical mutations in SMO, SUFU, or GLI2 that reactivate HH signaling, these alterations alone do not fully explain clinical variability in treatment response." (PMID 41543881, 2026). "Patients with high GLI2 and high DEC1 IHC scores in tumor tissue had the shortest OS." (PMID 40133270, 2025). "However, for DEC1 KD MKN-45 cells transfected with GLI2, CDDP-inhibited GC tumor growth less efficiently than the DEC1 KD MKN-45 group." (PMID 40133270, 2025). "However, when combined with GLI2 overexpression in the CDDP-treated group, there was partial restoration observed in terms of tumor volume and growth rate." (PMID 40133270, 2025). "An immunohistochemical analysis demonstrated the expression of Patched1, Gli1, and Gli2 in 70%, 70%, and 65% of human ONB cases, respectively, with Patched1 levels inversely and Gli1 levels positively correlating with the tumor severity based on Kadish staging and Hyams grading." (PMID 40710426, 2025). "Gli2-dominant Hh overexpression was seen in the tumour plus stroma of eyelid morphoeic but not nodular BCC." (PMID 41373535, 2025). "Advanced HNSCC tumours were shown to express higher levels of SHH, PTCH1, SMO, GLI1, GLI2 and GLI3." (PMID 39234399, 2024). "In tumor-induced skin, a single treatment with AFL monotherapy resulted in significant mean reductions of mRNA expression of all three hedgehog genes (Gli1, 72.4%, p = 0.003; Gli2, 55.2%, p = 0.010; Ptch1, 70.9, p < 0.001)." (PMID 38308119, 2024). "GLI2 knockdown using lentiviral-mediated shRNA downregulates genes related to HH and Wnt signalling pathways, including leucine-rich repeat-containing GPCR 5, inhibits tumour cell proliferation and invasive capacity, and induces apoptosis." (PMID 39568072, 2024). "Moreover, GLI1, GLI2, and GLI3 were significantly expressed in ten, ten, and thirteen tumor stages, respectively, suggesting their involvement in tumor progression." (PMID 38498906, 2024). "Our data confirm previous reports of tumor cells resembling non-cycling GCPs (GLI2 + /TOP2A-), cycling GCPs (GLI2 + /TOP2A + ), and differentiated cells (NeuN + )." (PMID 38191555, 2024). "We observed that all tissue cases exhibiting high GLI2 expression (score > 4) were of the tumor group, and its Area Under the Receiver Operating Characteristic (AUROC) curve value for GLI2 in distinguishing tumor tissues from normal tissues was 0.85 (p < 0.0001)." (PMID 38976559, 2024). "Similar analyses carried out on tumor cell lines indicated that GLI1 and GLI2 were significantly positively correlated in 15 of the tested cell lines, while GLI1 and GLI3 exhibited significant positive correlations in 6 cell lines, but a negative correlation in 1 cell line." (PMID 38498906, 2024).
tumor (continued). "Additionally, GLI2 and GLI3 displayed a significant positive correlation in 9 of the examined tumor cell lines." (PMID 38498906, 2024). "Based on these, we propose the hypothesis that M35L mutation possibly exchanges SPOP substrates from oncoproteins (such as GLI2, c-MYC and TRIM24) to tumor suppressors (such as IRF2BP2), therefore reprogramming the tumor properties of SPOP." (PMID 38409107, 2024). "Notably, autologous cultures of GLI2-expressing gastric organoids, dendritic cells and CTL treated with anti-PDL1 neutralizing antibody resulted in cytotoxic T cell-induced tumor apoptosis." (PMID 36674836, 2023). "In contrast, co-injecting Gli2/Gli3 KO fibroblasts with tumor cells fails to promote tumor growth, and produces tumors that are significantly smaller than tumors co-injected with WT fibroblasts." (PMID 35867772, 2022). "In addition to palbociclib, a recent study has revealed that THZ-1, a covalent inhibitor of CDK7, antagonizes GLI1 and GLI2 transcription, preventing the growth of SHH-driven MBs and SMO inhibitor-resistant human tumor cell lines in vivo and in vitro." (PMID 35573667, 2022). "Canonical activation of the pathway via genetic aberrations in pathway components and noncanonical activation of GLI1 and GLI2 transcription factors in tumor cells are oncogenic." (PMID 36010600, 2022). "To further verify the tumour-promoting role of the Hh signalling pathway in EOC, we firstly examined the effects of GANT61 (the specific inhibitor of Gli1 and Gli2) by measuring the expression of Hh receptor, Ptch, and effectors, Gli1 and Gli2." (PMID 36358596, 2022). "We therefore suspected that in the absence of T cells, the enhanced NK cell recruitment in our Gli2/Gli3 KO condition was responsible for antagonizing tumor growth." (PMID 35867772, 2022). "TdTomato expression was detected by IF in tumors from our Gli2/Gli3 KO fibroblast condition, confirming that the decrease in tumor growth was not simply due to the death of injected fibroblasts." (PMID 35867772, 2022). "Gli2, the major transcriptional activator of Hh signaling, whose localization and activity can be promoted by KIF7, was reported to function in skin development and tumor suppression." (PMID 34346563, 2021). "A positive hybridization signal for canine Smo and Gli2 gene expression was predominately cytoplasmic in the neoplastic cells, varying from very low to almost no signaling amongst tumor specimens." (PMID 32348319, 2020). "Finally, the in-vivo assay was conducted and the results revealed that circ-STAT3 promoted HB tumor growth via up-regulating STAT3 and Gli2." (PMID 32493490, 2020). "Based on all findings, Gli2-induced circ-STAT3 served as a ceRNA against miR-29a/b/c-3p to elevate STAT3 and Gli2 expression, thus facilitating cell proliferation, invasion, migration, stemness and tumor growth in HB." (PMID 32493490, 2020). "Interestingly, GLI2 inhibition sensitizes cells to cisplatin treatment and reduces tumor proliferation, and both CD105 and GLI2 are proposed as promising targets to overcome resistance." (PMID 31244888, 2019). "To test whether GLI2 induction is required to sustain growth of tumor cells following suppression of KRAS*, we stably overexpressed Flag-tagged mouse GLI2 in iKRAS cell lines (iKRAS-GLI2) prior to Dox withdrawal." (PMID 31134896, 2019). "Examination of main Hh target genes individually shows higher levels of GLI2, PTCH1, SMO, BOC, and HHIP transcripts in the tumor-adjacent tissue as compared to the bulk tumor, further supporting the importance of the tumor-adjacent tissue in the activity of Hh signaling." (PMID 31658643, 2019). "Higher expression of GLI2 was correlated with lower primary tumor stage (T1-2 vs. T3-4, p = 0.036), no lymphatic invasion (absent vs. present, p = 0.034), and no tumor recurrence (absent vs. present, p = 0.011)." (PMID 30081498, 2018).
tumor (continued). "Interestingly, in vivo GANT61 inhibition of Gli2-induced PD-L1 by tumor cells, resulted in increased CTL numbers within the tumor tissue." (PMID 30647844, 2018). "In mice that had GLI2 knocked down via transfection of GLI2-shRNA, tumor growth was decreased compared to mice that did not have GLI2 knocked down." (PMID 28061797, 2017). "Interestingly, we found that tumor cell proliferation-related genes of Wnt7a, SUFU, PTCH2, and Gli2 changed significantly." (PMID 28640224, 2017). "Interestingly, the genes of SUFU, Gli2, Wnt7a, and PTCH2 closely related to tumor cell proliferation were significantly upregulated." (PMID 28640224, 2017). "Gli-2 expression was recognized in the microvasculature in the tumor bone microenvironments of resected samples (data not shown)." (PMID 27007126, 2016). "Neither sex, history of nicotine or consumption of alcohol, age, tumor stage, n-status nor concomitant chemotherapy influenced expression of Gli-1 or Gli-2." (PMID 27918595, 2016). "Comparing papCP and adaCP tumor samples, the latter showed significant up-regulation of direct targets of the Wnt/β-catenin signaling pathway (LEF1 and AXIN2) as well as important components of the hedgehog signaling pathway (GLI2, PTCH1 and SHH)." (PMID 26927026, 2016). "Our group has published on TGFβ mediated activation of Gli2 in other tumor types that do not express the conical Hh signaling receptors, Smo and Ptch." (PMID 27738315, 2016). "Our data showed that the reduction in the GLI2 expression in vitro the B16F10/shTGF-β1 cells and in vivo tumor tissues may decrease the TGF-β1 target gene expression and may inhibit the pro-oncogenic activity downstream of the TGF-β signaling." (PMID 25895132, 2015). "Furthermore, GANT-61 inhibits PCSC-containing tumor growth, which is associated with upregulation of TRAIL-R1/DR4 and TRAIL-R2/DR5 expression and downregulation of Gli-1, Gli-2, Bcl-2, and ZEB1 expression in tumor samples obtained from nude mouse xenografts." (PMID 24325450, 2013). "One possible mechanism is through activation of GLI2 by the ERK and AKT pathways in tumor cells." (PMID 22859956, 2012). "Finally, we show upregulated Gli2 dominant Hh signalling is characteristic of both the tumour and the stroma in mBCC but not nBCC." (PMID 41373535, 2025). "TGFβ3/GLI2/YAP1 expression was associated with anti-tumor immune desertion, as evident by a negative association with tumor-infiltrating lymphocytes, including the CD8 T cells, CD4 T cells, B cells, Th1, gamma delta T cells (γδ T cells), and T follicular helper cells (Tfh)." (PMID 40027190, 2025). "It is interesting that we could not detect GLI2 in any of the samples, in the epidermal layer, or in the tumor itself." (PMID 38892279, 2024). "Finally, GLI2 and GLI3 exhibited a significant positive correlation in 29 tumor tissues." (PMID 38498906, 2024). "However, we observed a significant increase in Gli2 expression in DDLPS tumors compared to WDLPS tumors, leading us to hypothesize that Gli2 may play a greater functional role in tumor dedifferentiation compared to Gli1." (PMID 37444470, 2023). "Furthermore, overexpression of GLI1, GLI2, PTCH1, and SMO was correlated with a higher histological grade of the tumor, what may suggest that HH signaling plays a key role in HNSCC malignancy." (PMID 37626893, 2023). "Interestingly, a novel PTCH1::GLI2 fusion rather than MALAT1-GLI1 fusion was detected in the tumor by RNA-based next generation sequencing (NGS)." (PMID 36147912, 2022). "Plasma and tumor tissue samples from immune checkpoint inhibitor (pembrolizumab and nivolumab)-treated NSCLC patients revealed elevated levels of Wnt and SHH in plasma as well as increased GLI2 levels, suggesting HH and Wnt activation was correlated with immune therapy resistance." (PMID 34831357, 2021).
tumor (continued). "In accordance with the in vitro data, further detailed analysis of the tumor tissues revealed that the MDR1 and proliferating cell nuclear antigen (PCNA) protein levels were decreased, whereas the γH2AX and apoptosis protein Bcl2 levels were upregulated in the mouse tumors upon Gli2 knockdown." (PMID 35059317, 2021). "Thus, the purpose of this work was to evaluate the antitumoral activity of GANT61, a downstream inhibitor of the HH pathway, on the gene and protein expression of HH pathway components (PTCH1, GLI1, GLI2, and GLI3), as well as tumor cell proliferation and death in a metastatic OSCC cell line." (PMID 32846867, 2020). "Also, in the cerebellum, deletion of Spop increases Gli2 protein levels, but does not contribute to increased Gli2-mediated proliferation of granule cell progenitors or induce tumor formation, unless combined with SuFu deletion." (PMID 30754706, 2019). "In 2014, Yang reported on the lncRNA BCAR4 (breast-cancer anti-estrogen resistance 4), which simultaneously binds to the transcription factor SNIP1 (Smad nuclear interacting protein 1) and the phosphatase 1 nuclear- Targeting subunit (PNUTS), and it regulates the hedgehog/GLI2 signaling pathway." (PMID 28212533, 2017). "Notably, several basal progenitor state factors (Hoxc13, Pax9, Gli2, Krt15) displayed paradoxical downregulation, indicating that EY-driven transcriptional changes do not reflect a physiologic OEPC cell state, but rather constitute a unique cellular state related to tumor initiation." (PMID 37961717, 2023). "Conversely, conditional Rosa26 knock-in allele of GLI3T, which was proven to downregulate GLI1 and GLI2 expression in NIH 3T3 cells, resulted in reduced PANIN lesion formation, reduced proliferative pancreatic cells (absence of Ki67 staining), and delayed PDAC tumor formation." (PMID 34572373, 2021). "Therefore, the inhibitory effect of Xiaoaiping on tumor growth may be achieved by enhancing the autophagy and apoptosis of HCC cells, as well as reducing its cellular activity via the downregulation of Gli1 and Gli2." (PMID 31341493, 2019). "Consistently, tumor biopsies of BCC showed a 10q deletion containing SUFU, which was associated with the partial loss of SUFU function but was not sufficient to drive resistance to vismodegib in the absence of other co-occurring alterations, such as focal GLI2 amplifications." (PMID 30558232, 2018). "However, while the expression of GLI2 was confirmed at the protein level in tumor material extracted from P1, no fresh frozen material was available to perform the analysis in P2 and we cannot conclude if the higher RNA expression in P2 corresponds to a higher protein expression." (PMID 29371980, 2017). "Independent of tumor characteristics, such as histology and grades, higher expressions of SHH, PTCH1, PTCH2, and GLI1 have shown beneficial prognostic influence, whereas GLI2, GLI3, and SUFU are correlated with adverse clinical outcomes in OC patients." (PMID 40565349, 2025). "We screen out GLI2 is a key ARG that promotes drug tolerance and tumor immunity escape via the TGF-beta/non-classical Hedgehog signaling pathway." (PMID 38159250, 2023). "In this study, the treatment with LDE225, the SMO inhibitor, showed an inefficient suppression of LMS tumor growth, concomitantly with no changes in SMO and Ki67 protein expression, as well as in gene expression of SMO, GLI1, and GLI2." (PMID 34642915, 2022). "Immunohistochemical analysis showed tumor cells positive for BMP-2, osteonectin, osteocalcin, AE1/AE3, TGF-β1, Gli2, Smad2/3, and CDX2 and negative for nestin, CD56, and CK7." (PMID 33388078, 2021).